CDK4 (cyclin dependent kinase 4)
Diseases named in the same sentence as CDK4 in open-access papers (continued):
Sharing a sentence is not in itself a finding about the gene and the disease.
tumor (continued). "In addition, several pre-clinical tests, including a novel ex vivo organotypic tumor spheroid culture system and multiple in vivo murine syngeneic models, has shown that CDK4/6 inhibition augments the response to PD-1 blockade, thereby providing a rationale for combining CDK4/6i and ICI." (PMID 41465595, 2025). "Additionally, CDK4/6 inhibition may re-sensitise tumours to PI3K blockade." (PMID 40563591, 2025). "Availability of small molecule inhibitors of CDK4/6 enables a combination strategy that co-targets CDK4/6 and KRAS-G12C, and its potential was preclinically demonstrated in flank tumor models." (PMID 40317086, 2025). "We hypothesized that tumours exhibiting exceptionally high ER expression (≥90%) represent a subset with maximal endocrine sensitivity, which may, in turn, translate to a superior response to the synergistic blockade of both the ER pathway and the cell cycle via CDK4/6 inhibitors." (PMID 41440236, 2025). "Consistent with several reports that the TME can drive therapeutic resistance and disease progression even in TNBC, tumour–stroma interactions have been shown to modulate the sensitivity of TNBC cells to diverse drugs, including CDK4/6 inhibitors." (PMID 41388212, 2025). "Selective CDK4/6 inhibitors, including palbociclib, abemaciclib, and ribociclib, have demonstrated efficacy in treating primary HER2-positive tumours and in predicting resistance to HER2-targeted therapies." (PMID 40004024, 2025). "Mechanistically, CDK4/6 directly phosphorylates DUB3, enhancing its deubiquitinase activity towards YAP1, which promotes tumor growth and contributes to chemo-resistance in HCC." (PMID 40307228, 2025). "This is the longest course of CDK4/6 inhibitor treatment for EBC and was chosen to maximise the exposure of circulating tumour cells to ribociclib." (PMID 40002156, 2025). "Molecular insights into the tumor’s amplification of MDM2 and CDK4 suggest potential therapeutic targets for novel treatments such as CDK4/6 inhibitors and MDM2 inhibitors, which are currently under investigation." (PMID 40165894, 2025). "Combining CDK4/6 and CDK2 inhibitors with the CXCR1/2 antagonist, SX-682, halted B16F10 tumor growth by blocking tumor cell proliferation and increasing the anti-tumor immune response in the tumor microenvironment." (PMID 40904502, 2025). "In these patients, CDK4/6 inhibitors triggered a robust immune response in terms of elevated levels of both CD4 + T cells and anti-tumour CD137 +/CD8 + T cells." (PMID 41388212, 2025). "Based on a biological rationale suggesting that tumours with exceptionally high ER expression might exhibit maximal dependence on the ER pathway, we specifically hypothesised that an ER expression threshold of ≥90% would identify patients deriving superior benefit from CDK4/6 inhibition." (PMID 41440236, 2025). "Senescent tumor cells can also secrete an immunosuppressive SASP, including interleukin-18, CXCL-1, and CCL-20, by CDK4/6is, increasing the infiltration of MDSCs and leading to an immunosuppressive microenvironment." (PMID 41463246, 2025). "Additionally, these results have implications for current and emerging clinical trials.Specifically, a recent clinical trial with the CDK4/6i Abemaciclib in EC suggested thatTP53 mutations in the tumor may predict lack of response." (PMID 39932274, 2025). "Preclinical models have demonstrated that uPAR-targeted CAR-T cells efficiently eliminate senescent tumor cells induced by MEK and CDK4/6 inhibition, thereby suppressing tumor progression in lung cancer models." (PMID 40867884, 2025). "When combined with abemaciclib (a CDK4/6 inhibitor), alpelisib (a PI3K inhibitor), or everolimus (a mTOR inhibitor), imlunestrant demonstrates enhanced anti-tumor efficacy, including against brain metastases, irrespective of ESR1-mutation status." (PMID 40641933, 2025).
tumor (continued). "Another study also reported that a combination of MEK and CDK4/6 inhibitors with an immune checkpoint blockade suppressed PDAC proliferation through the induction of senescence and the SASP modulating tumor vasculature and the immune system." (PMID 40862837, 2025). "Upregulation of miR-142-3p suppressed growth of CRC cells and xenograft tumor by downregulating CD133, ABCG2, and Lgr5, CDK4, and CTNNB1." (PMID 40868120, 2025). "By contrast, mice treated with the C‐PC, and to a greater extent the C‐P, CDK4/6i priming regimens displayed higher CD4+ and CD8+ T cell abundance versus either monotherapy and other treatment groups in all three tumor models." (PMID 40936164, 2025). "Consistently, blocking Ser41 phosphorylation, either by CDK4/6 inhibition or the reconstitution of the Ser41A mutant, promotes YAP1 degradation and suppresses YAP1‐driven tumor progression." (PMID 39968498, 2025). "The proposed mechanisms include the inhibition of CDK4 and CDK6, blocking Rb phosphorylation, and preventing tumor cells from entering the S phase, thereby inhibiting tumor growth." (PMID 40416598, 2025). "By analyzing metastatic biopsies, both prior to and during tumor progression on CDK4/6is, scRNA-seq allowed us to unravel the intricate landscape of the TME and the interactions between tumor and immune cells." (PMID 39955556, 2025). "The inhibition of cyclin-dependent kinase 4/6 (CDK4/6) activity blocks cell cycle progression, leading to G1 arrest and the inhibition of tumor cell proliferation." (PMID 40005476, 2025). "Based on this logic, combining a HIF2 inhibitor with a CDK4/6 inhibitor should be additive or synergistic, at least in ccRCCs that are intrinsically HIF2-dependent, leading to deeper and more frequent tumor regressions." (PMID 40178040, 2025). "Our study, using genetic and pharmacological approaches, reveals that CDK4 inactivation only modestly impacts TNBC cell proliferation and tumor formation." (PMID 39788939, 2025). "We treated HCC1806 and SUM149PT cells with CDK4/6 inhibitors (Palbociclib, Ribociclib and Abemaciclib) and KPT‐330, they all showed good anti‐tumor activity, Abemaciclib was more effective than the other two drugs." (PMID 39888288, 2025). "Combining RAS(ON) and CDK4/6 inhibition with a CD40 agonist results in durable regressions and CD4 T cell–dependent tumor-immune equilibrium." (PMID 40299790, 2025). "Palbociclib, a CDK4/6 inhibitor, enhances SPOP degradation and improves anti-tumor immunity in in vivo models." (PMID 39851497, 2025). "Additionally, although the combined inhibition of BRAF, MEK, and CDK4/6 has shown promising anti-tumor effects, flow cytometry analysis has indicated that the massive infiltration of tumor-infiltrating myeloid cells may have an adverse impact on anti-tumor immunity in melanoma." (PMID 41463246, 2025). "Palbociclib, a clinically‐approved CDK4/6 inhibitor, is used to induce senescence in a murine TNBC model, resulting in both tumor growth arrest and increased heat sensitivity due to HSP70 downregulation." (PMID 40801385, 2025). "Immunohistochemically, the tumor cells were positive for p16, mouse double minute 2 (MDM2), and cyclin-dependent kinase 4 (CDK4)." (PMID 39974236, 2025). "FBXW7 was the most recurrently observed F-box protein among K562 hits, paired with many cell cycle related proteins (e.g. CDK2AP1, CDK4, CDKN1A, CKS1B), consistent with the known role of FBXW7 as a tumor suppressor." (PMID 39919746, 2025). "CDK4/6is mediate tumor cell senescence to release immunostimulatory SASP, achieving the connection between tumor cells and immune cells in the microenvironment, while inhibiting angiogenesis." (PMID 41463246, 2025). "Huaier supplementation increased Akkermansia abundance and its metabolite butyrate, which synergized with a CDK4/6 inhibitor to boost CD8^+ T-cell infiltration and tumor suppression." (PMID 40599546, 2025).
tumor (continued). "Another highly relevant activity for cancer progression is the ability of CDK4 and CDK6 to suppress senescence by phosphorylating FOXM1, maintaining cell cycle progression and preventing tumor suppressive mechanisms." (PMID 39800748, 2025). "The E-KTS isoform binds to and regulates expression of CCND1, which in turn activates CDK4/6, enabling DSRCT cells to overcome the RB tumor suppressor and proliferate." (PMID 39139449, 2024). "In this study, we show the potential effect of CDK4/6 inhibitors (palbociclib and ribociclib) on SCLC chemoresistance and tumor growth through SCLC mouse models and SCLC PDX models." (PMID 39136283, 2024). "In a recent study, Shi and colleagues assessed the efficiency of another CDK4/6 inhibitor dalpiciclib in head and neck mucosal melanoma (HNMM) patients with CDK4 amplification using PDX mouse models and patient-derived tumor cells (PDCs)." (PMID 39598629, 2024). "Preclinical studies have demonstrated that BRG1 inactivation increases tumor invasiveness and enhances sensitivity to targeted agents inhibiting oxidative phosphorylation and drugs targeting EZH2, AURKA, ATR, CDK4, and CDK6." (PMID 39465834, 2024). "In this review, we delve into the diagnosis and therapeutic implications of neoplasms with genetic alterations involving the chromosomal region 12q13-15, mainly MDM2, CDK4, and GLI1." (PMID 38275873, 2024). "Other tumour growth-related genes, such as Myb, KRAS, Akt-3, and CDK4 were also downregulated by the three BRD4 inhibitors in PDAC cells." (PMID 38279262, 2024). "There results indicated that domperidone inhibited tumor growth by suppressing MEK/ERK and CDK4/SMAD3 pathways via targeting MEK1/2 and CDK4." (PMID 38528618, 2024). "Recent studies have identified novel CDK4/CDK6 inhibitors with improved efficacy in inhibiting MM cell proliferation and tumor growth." (PMID 39664374, 2024). "The combination of CDK4/6 and PI3K inhibitors leads to a synergistic reduction in cell viability and tumor growth and has been reported to overcome drug resistance." (PMID 39461947, 2024). "Like our transgenic model of CDK4/6i resistance derived in situ, treatment of this PDX with the CDK4/6i ribociclib or with INX-315 slowed tumor growth modestly, but their combination was significantly more effective." (PMID 38047585, 2024). "For example, the interaction between CDK4/6 and the transcription factor MYC plays a synergistic role in promoting tumor cell proliferation and metastasis." (PMID 38890443, 2024). "The previous study showed that CDK4/6 inhibition facilitates ubiquitination of ZEB1, a key molecule in tumor metastasis, via suppressing activation of the deubiquitinase USP51." (PMID 38596406, 2024). "Inhibitors of cyclin-dependent kinase 4/6 (CDK4/6) have shown promise in halting the cell cycle in the G1 phase and effectively inhibiting tumor proliferation." (PMID 38927583, 2024). "For example, CDK4, CDK6, and CDK7 can influence immunotherapy efficacy by affecting the tumor microenvironment (TME)." (PMID 39371450, 2024). "The copy numbers of shared CNVs, such as PDGFRA/KIT, CDK4, MYC, KRAS, and VEGFR2, were highly consistent (Pearson correlation = 0.95, P = 0) between the CSF and tumor tissues." (PMID 38388726, 2024). "CDK4 and CDK6 play a key role in mammalian cell proliferation by working in complex with CCND1 to phosphorylate and inhibit RB1 tumor-suppressor activity during early G1 phase." (PMID 38507413, 2024). "The top five differential genes in LumB tumours, ranked by significance, are MIS18A, WIF1, CHEK2, EMCN and CDK4." (PMID 38332687, 2024).
tumor (continued). "To further explore the expression of SelK and its downstream genes with respect to expression correlation, we initially analyzed the expression levels of CDK4, β-TrCP1, and GRP78 in nude mice tumor tissue samples using IHC." (PMID 39155374, 2024). "Our previous studies have demonstrated robust anti-tumor effects of cyclin-dependent kinase 4/6 (CDK 4/6) inhibitors in head and neck MM (HNMM) patient-derived xenograft models with CDK4 amplification." (PMID 38807144, 2024). "Amplification of or mRNA overexpression of CDK4, CDK6 and/or cyclin D1 was observed in 16% of tumours." (PMID 38612869, 2024). "Cyclin-dependent kinase 4/6 (CDK4/6) is a downstream target of activated/phosphorylated ERK and there is evidence for anti-tumor activity of the dual ERK and CDK4/6 inhibition, using ulixertinib and palbociclib, respectively." (PMID 38338909, 2024). "That possibility was tested by combining PD-L1 antibody therapy with CDK4/6-MEK inhibition, which did indeed elicit impressive anti-tumor effects." (PMID 39347707, 2024). "CDK4/6 also phosphorylates and activates the transcription factor FOXM1, further promoting cell proliferation and tumor development." (PMID 38890443, 2024). "These signaling pathways can then directly induce MYC activity and subsequently stimulate the activity of critical nuclear factors that govern tumor migration and invasion, of which the activity of E2F1, CDK4, p27, and p15 stands out." (PMID 38204280, 2024). "With these data, we were able to conduct a unique correlative study between gene expression, the tumor microenvironment, and CCCA status with both CDK4/6 inhibition and standard-of-care AC-T neoadjuvant therapy." (PMID 38448600, 2024). "Inhibitors of cyclin-dependent kinase 4/6 (CDK4/6) have been shown to halt the cell cycle in the G1 phase and inhibit tumor proliferation." (PMID 38542190, 2024). "AZD9496 was more effective at inhibiting tumor growth when combined with the PI3K pathway inhibitors and a CDK4/6 inhibitor." (PMID 38339371, 2024). "The cell cycle in tumors is modulated by c-Myc, which regulates the expression of downstream target molecules, including cyclin D1/2, cyclin E1, CDK4, cdc25A, and E2F1, and promotes tumor growth." (PMID 39085875, 2024). "The histopathological findings of our patient’s surgical specimen showed the proliferation of mature and variously sized adipocytes and ectopic ossification, and the immunohistochemical staining indicated that tumor nuclei were positive for MDM2 and CDK4." (PMID 39109289, 2024). "In agreement with our flow cytometry findings, we found that DYRK1A inhibition leads to increase in expression of G1/S regulators (i.e. Cyclin D1, and CDK4) and a decrease in expression of CENP-A in tumor samples." (PMID 38839871, 2024). "Consistently, Ki67, MMP2, MMP9, c-Myc, β-catenin, CDK4, CDK6, and Cyclin D1 protein levels in tumor tissues were significantly decreased by SAMD5 overexpression but partially increased by PLK1 overexpression." (PMID 39524172, 2024). "For instance, tumor sample CCGA-UBC-034T contained an ecDNA with seven genes, including CDK4, DDIT3, GLI1, HMGA2, PTPN11, RFC5, and TMPO." (PMID 39267784, 2024). "For this commentary, we will discuss evidence supporting combination therapies against CDK4/6 and MEK for treating MPNSTs and their contribution toward anti-tumor immunity." (PMID 39347707, 2024). "Our study showed that knockdown of eIF3a reduced the CDK4 and CDK6 expression in DLBCL cells, suggesting that targeting eIF3a has a potential anti-tumor effect in DLBCL." (PMID 38589831, 2024). "This suggests a potential therapeutic strategy combining CDK4/CDK6 inhibitors with SETDB1 and TRIM28 modulators to stabilize pRB and suppress tumor growth." (PMID 39664374, 2024). "The results showed that the suppressive effect of domperidone on tumor growth restored in cell lines with knockdown of MEK1, MEK2, or CDK4." (PMID 38528618, 2024).
tumor (continued). "Our data show that combined inhibition of CDK4 and PIN1 permits deeper and longer-lasting remissions, even resulting in complete remission in some tumor-bearing mice." (PMID 38622115, 2024). "Analysis of this patient’s tumor showed high levels of amplification of MDM2 and CDK4 likely indicating that despite the unique morphological features, bone formation shared many of the cytogenetic features of the common forms of DDL." (PMID 39687824, 2024). "More importantly, a combination with small-molecule inhibitors of CDK4/6 (palbociclib, abemaciclib, or ribociclib), PI3K (alpelisib or inavolisib), or mTOR (everolimus) produced robust tumor regressions in most cases." (PMID 39767607, 2024). "Overall, our clinical and laboratorial studies identified the similar but distinct role of CDK4 and CDK6 in anti-tumor responses." (PMID 37833461, 2023). "To further investigate the antitumor efficacy of co-targeting CDK4/6 and PD-1, we constructed a LLC1-shLkb1-luc cell line and established in situ tumor models, followed by different treatment arms." (PMID 36871040, 2023). "Apart from exploring immune checkpoints as tumor biomarkers for predicting disease prognosis, researchers also explored combination therapy based on anti-PD-1 antibodies, such as anti-angiogenesis targeting therapy and CDK4/6 inhibitor which could help improve clinical outcomes." (PMID 37430294, 2023). "Cyclin-dependent kinases CDK4 and CDK6 not only contribute to cell cycle progression but also participate in cell metabolism, immunogenicity and anti-tumor immune responses." (PMID 37686364, 2023). "Studies have shown that β-catenin signaling pathway can promote proliferation and metastasis of tumor cells by activating the transcription of various oncogenes, such as MMP9, C-myc, and CDK4." (PMID 37460940, 2023). "We found that CDK4 and PHF6 were decreased in tumours from mice implanted with PHF6 KD cells compared with controls." (PMID 36756714, 2023). "miR‐31 mediated QKI‐5 downregulation promoted tumor growth of NSCLC through regulating p21 protein and CDK4/6 mRNAs." (PMID 36172919, 2023). "We aim to find the similarities and differences between CDK4 and CDK6 in regulating tumor immunogenicity." (PMID 37833461, 2023). "On the other hand, in KIRP, CDK1, CDK4, HIPK2 and MYC expression increased with the pathological and clinical stage of the tumor, whereas KLF4 decreased." (PMID 37047552, 2023). "For instance, the combination of Palbociclib (an oral CDK4/6 inhibitor) and GDC-9545 (an oral SERD) demonstrated significant efficacy in a mouse tumor model, resulting in up to a 24% reduction in tumor size or degradation." (PMID 37808197, 2023). "CDK4/6 inhibitors inhibit the CDK1-Cyclin D4 complex, which induces cell cycle arrest in the G1 phase and apoptosis in some tumor cells." (PMID 37305685, 2023). "The combined therapy of abemaciclib and olaparib synergistically suppressed tumor growth in the xenograft model, and samples derived from animal tumors were used to confirm the key role of PARP1 in CDK4/6i resistance by immunohistochemical assay." (PMID 38037159, 2023). "To explore this, we re-scored tumours based on gene expression programmes specific to serum starvation, contact inhibition, MEK inhibition, CDK4/6 inhibition or spontaneously occurring quiescence as defined by Min and Spencer (see ‘Methods’)." (PMID 37221612, 2023). "In the current studies, we addressed the mechanisms responsible for the anti-tumor immunity of CDK4 and CDK6 blockage using Cdk4−/− and Cdk6−/− tumor cells." (PMID 37833461, 2023). "Cell viability assay found that CDK4/6 inhibitor and PDGFR inhibitor potently decreased cell viability in recurrent tumor cells, as compared to primary tumor cells." (PMID 38012788, 2023).